IL32 (interleukin 32)
Diseases named in the same sentence as IL32 in open-access papers (continued):
Sharing a sentence is not in itself a finding about the gene and the disease.
infectious disease (8 papers, 2017 to 2025). A disorder directly resulting from the presence and activity of a microbial, viral, or parasitic agent in humans. "IL-32 is associated with the control or immunopathology of numerous infectious diseases, such as tuberculosis, HIV/AIDS, leprosy and hepatitis likewise in dermatological diseases." (PMID 28709468, 2017). "Given the emerging role of IL-32 variants in diverse pathological processes, including inflammatory conditions, infectious diseases, and immune imbalances in HIV infection, the elucidation of IL-32 (3D) structures and domain interactions has become a high priority." (PMID 41383621, 2025). "The role of IL-32 has been, so far, investigated in several inflammatory and infectious diseases, including different leishmaniases." (PMID 35309341, 2022). "Thus, the use of an experimental animal model to study the role of IL-32 in inflammatory and infectious diseases is made possible by IL-32 humanized transgenic mice." (PMID 28709468, 2017). "The major challenge in the study of the mechanisms and biological activities of IL-32 in infectious diseases is the lack of a known receptor for IL-32." (PMID 35309341, 2022).
inflammation (7 papers, 2012 to 2023). Aberrant reaction of the microcirculation characterized by movement of fluid and leukocytes from the blood into extravascular tissues. "Vascular inflammation is further promoted by the expression of endothelial cell adhesion molecules, which are induced by adipokines such as interleukin 32 (IL-32), visfatin, IL-1β, and the tumor necrosis factor (TNF)." (PMID 31694146, 2019). "Ileal tissue from patients with AS who had chronic intestinal inflammation revealed higher expression of IL-32 than that from patients with AS without chronic intestinal inflammation, and healthy controls." (PMID 36875066, 2023).
bacterial infection (5 papers, 2016 to 2025). "The relationship between IL-32 levels and SARS-CoV-2 or bacterial infections, alongside underlying etiological conditions, was assessed." (PMID 40149726, 2025). "However, the function and expression of IL-32 in other bacterial infections remain poorly understood." (PMID 40149726, 2025). "The proinflammatory role of IL-32 in viral and some bacterial infections was confirmed recently, but no published data were found about its role in UTI." (PMID 29134126, 2017).
metabolic disorders (4 papers, 2020 to 2026). "Another perspective will be to investigate the contribution of IL32 in the biological disorders underlying the dysfunctions of muscle cells, for example, inflammation, impairment of myogenesis or metabolic disorders." (PMID 41457346, 2026).
immune diseases (2 papers, 2021 to 2022). "The addition of Wenyang Huazhuo Tuihuang Decoction can reduce the proinflammatory factor IL-32 level and increase the inflammation inhibitory factor IL-10 level in patients with HBV-related ACLF, which has a certain regulatory effect on immune disorders." (PMID 35399641, 2022).
bone disorder (1 paper, 2009). "The complex role of IL-32 in the patho-physiology of bone disorder therefore requires further clarification prior to the development of any potential therapeutic approach." (PMID 19137064, 2009).
connective tissue diseases (1 paper, 2023). "Putative role of IL-32 as a biomarker in connective tissue diseases." (PMID 36875066, 2023).
gastrointestinal tumors (1 paper, 2021). "The upregulation in tumors and in the adjacent tissue may serve different purposes, as was suggested for IL32, the overexpression of which in gastrointestinal tumors reflected proliferative and metastatic potential, and antiapoptotic and immunosuppressive capacity in non-transformed mucosa." (PMID 34885960, 2021).
renal diseases (1 paper, 2016). "The results demonstrated that IL-32 was detectable in only 3 patients and led to the speculation that IL-32γ possibly contributes to the pathogenesis of renal diseases in patients with SLE." (PMID 27069296, 2016).
IL32 also shares sentences with these, for which no sentence is quoted: Allergy (8 papers); multiple myeloma (7); type 2 diabetes (7); mesothelioma (6); laryngeal squamous cell carcinoma (3); Lewis Lung Carcinoma (3); metabolic syndrome (3); colon adenocarcinoma (2); dermatitis (2); graft versus host disease (2); heart disease (2); Hepatic steatosis (2); hidradenitis suppurativa (2); laryngeal carcinoma (2); liver cancer (2); metabolic dysfunction-associated steatohepatitis (2); small cell lung carcinoma (2); squamous cell carcinoma (2); ulcerative colitis (2); Acute hepatitis (1); adenocarcinoma (1); AIDS (1); alopecia areata (1); amyloid (1); Ataxia (1); autism (1); bone cancer (1); brain cancer (1); cerebellar ataxia (1); Cerebellar atrophy (1).
A further 53 diseases each share a sentence with IL32 in 1 paper.